SMYD5 (SMYD family member 5)
Diseases named in the same sentence as SMYD5 in open-access papers (continued):
Sharing a sentence is not in itself a finding about the gene and the disease.
tumor (4 papers, 2021 to 2025). "These associations suggest that SMYD5 not only affects tumor biology but also impacts the tumor microenvironment and patient outcomes, aligning with earlier findings." (PMID 40872497, 2025). "Overall, these findings underscore the importance of SMYD5 in shaping the tumor immune landscape and its implications in improving anti-tumor immune responses." (PMID 40872497, 2025). "The results showed a marked increase in SMYD5 protein levels in LIHC tumor tissues compared to normal tissues." (PMID 40872497, 2025). "To highlight the potential role of SMYD5 in shaping the tumor immune microenvironment, we analyzed the correlation between SMYD5 expression and tumor-infiltrating lymphocytes (TILs)." (PMID 40872497, 2025). "The high expression levels of SMYD5 not only correlate with adverse clinical outcomes but also play an active role in modulating the tumor microenvironment, influencing immune responses and tumor cell behavior." (PMID 40872497, 2025). "Further mechanistic investigations are necessary to elucidate the molecular pathways by which SMYD5 influences tumor behavior." (PMID 40872497, 2025). "The scatter plot reveals a positive relationship (R = 0.17, p = 0.0024), indicating that higher SMYD5 levels are associated with an increased TIL presence, suggesting a potential role for SMYD5 in modulating the tumor immune microenvironment." (PMID 40872497, 2025). "This discovery highlights potential pathways for therapeutic interventions aimed at modulating SMYD5’s influence on tumor biology." (PMID 40872497, 2025). "We established that SMYD5 expression is significantly elevated in tumor tissues compared to corresponding normal tissues, confirming its potential role in oncogenesis." (PMID 40872497, 2025). "By contrast, SMYD5 ablation led to a significant reduction of overall tumor sizes and tumor burden with fewer tumor nodules noted." (PMID 39103523, 2024). "The analysis revealed predominant cytoplasmic staining of SMYD5, which was significantly elevated in 56% of tumor (T) samples and lower in only 6% of the tumor (T) samples compared to adjacent paratumor (P) tissues." (PMID 39103523, 2024). "The liver/body weight ratio, a common indicator of total HCC tumor burden, was also significantly lower in Smyd5 KO animals." (PMID 39103523, 2024). "While overexpression of Nras and Ctnnb1 promoted tumorigenesis in the mouse liver, knockdown of Smyd5 suppressed tumor formation." (PMID 35680905, 2022). "To further demonstrate the function of Smyd5 in tumor formation, we knocked down Smyd5 and rescued its expression with Smyd5-FL or Smyd5-ΔC." (PMID 35680905, 2022). "Furthermore, paired clinical samples demonstrated SMYD5 gene expression was significantly increased in multiple tumor types relative to their matched normal tissues." (PMID 40872497, 2025). "Our results demonstrated that silencing SMYD5 significantly reduces the migratory and invasive capacities of Hep3B cells, suggesting that it may facilitate tumor dissemination." (PMID 40872497, 2025). "Furthermore, a major limitation of this study is the lack of in vivo validation, which would provide a more comprehensive understanding of SMYD5’s functional role in the tumor microenvironment." (PMID 40872497, 2025). "Importantly, the SMYD5 dependency of SNU499 xenograft tumor growth was further magnified by Torin1 treatment as well." (PMID 39103523, 2024). "The OS and RFS of LIHC patients with SMYD5 overexpression were significantly prolonged, indicating that SMYD5 may be a potential tumor marker and therapeutic target for immune and targeted therapy in ESCA and LIHC patients." (PMID 34335697, 2021). "Importantly, our analysis reveals a significant positive correlation between higher SMYD5 levels and TILs, suggesting that SMYD5 may modulate the tumor immune microenvironment." (PMID 40872497, 2025).
tumor (continued). "Notably, combining SMYD5 knockdown with BRD4 inhibition using (+)-JQ1 enhances anti-tumor effects significantly, indicating a synergistic interaction that could be exploited for therapeutic benefit." (PMID 40872497, 2025). "This consistent upregulation of SMYD5 in both LIHC tumor tissues and cell lines (HepG2 and Hep3B) relative to the normal hepatic stellate cell line LX-2 underscores its potential role as a promoter of hepatocarcinogenesis." (PMID 40872497, 2025). "To confirm the overexpression of SMYD5 in LIHC, we analyzed immunohistochemical staining and protein expression of LIHC tumor tissues and normal tissues from the Human Protein Atlas (HPA) and Clinical Proteomic Tumor Analysis Consortium (CPTAC)." (PMID 40872497, 2025). "Our analysis confirmed that SMYD5 is overexpressed in LIHC tissues compared to adjacent normal tissues, as established through immunohistochemical staining and protein expression profiling using data from the Human Protein Atlas (HPA) and the Clinical Proteomic Tumor Analysis Consortium (CPTAC)." (PMID 40872497, 2025). "Consequently, combined targeting of SMYD5 and BRD4 may enhance anti-tumor effects, reinforcing the potential for dual-targeted approaches." (PMID 40872497, 2025). "The intensity of SMYD5 staining inversely correlated with overall survival and disease-free survival rates, consistent with previous reports.13,14 Like SMYD5, RPL40 K22me3 is elevated in 53.4% and attenuated in 5.0% of the tumor (T) samples compared to adjacent paratumor (P) tissues." (PMID 39103523, 2024).
SMYD5 also shares sentences with these, for which no sentence is quoted: head and neck squamous cell carcinoma (2 papers); lung squamous cell carcinoma (2); adrenocortical carcinoma (1); colorectal cancer (1); diffuse large B-cell lymphoma (1); glioma (1); liver fibrosis (1); ovarian carcinoma (1); sarcoma (1); testicular germ cell tumor (1); thymoma (1); uterine carcinosarcoma (1); uterine corpus endometrial carcinoma (1).